TIMP2 (TIMP metallopeptidase inhibitor 2)
Diseases named in the same sentence as TIMP2 in open-access papers (continued):
Sharing a sentence is not in itself a finding about the gene and the disease.
melanoma (continued). "Several studies have shown that melanoma cells can express a specific pool of MMPs (MMP-1, MMP-2, MMP-9, MMP-13, and MT1-MMP) as well as their tissue inhibitors (TIMP-1, TIMP-2, and TIMP-3)." (PMID 39594665, 2024). "Nevertheless, overexpression of EphB4 in A375 melanoma cells also influenced expression of 9 angiogenesis-related proteins (Ang-1, VEGF, Akt/PKB, TIMP-1, TIMP-2, TIMP-3, IL-8, TGF-β2, TGF-β R3)." (PMID 33153234, 2020). "We also determined the potential of C. molossus GAG to lessen activities of tissue inhibitor metalloprotease (TIMP-2), an inflammation marker, in HMVEC ells and melanoma cells." (PMID 30611221, 2019). "In the present study, we demonstrated that the signal transduction pathways in bornyl cis-4-hydroxycinnamate-treated melanoma cells involve up-regulation of TIMP-1 and TIMP-2 proteins and down-regulation of uPA protein." (PMID 30042328, 2018). "Furthermore, complexes containing AP-15 and therapeutic plasmid, encoding the TIMP metallopeptidase inhibitor 2 (TIMP2), introduced the TIMP2 gene with high efficiency to B16-F10 melanoma cells but not to B16-F10 melanoma tumors in C57BL/6 mice, as confirmed by TIMP2 protein level determination." (PMID 27088717, 2016). "In the present study we show that CoQ0 treatment significantly inhibits melanoma migration and invasion by down-regulating MMP-2, MMP-9 and up-regulating TIMP-1 and TIMP-2 expressions." (PMID 26968952, 2016). "TIMP-2 has been shown to stimulate A549 lung adenocarcinoma cell, HT1080 fibrosarcoma cell, MG-63 osteosarcoma cell, and A2058 melanoma cell proliferation." (PMID 26556867, 2015). "Consistent with previous observations in melanoma cells and human microvascular endothelial cells, we demonstrated that cell proliferation was potently downregulated in HSA/TIMP-2-treated tumor tissue as well as HUVECs." (PMID 22545131, 2012). "In agreement with a previous study of B16BL6 melanoma xenografts, systemic administration of HSA/TIMP-2 protein also demonstrated a potent anticancer effect in MLL prostate cancer xenografts." (PMID 22545131, 2012). "Additionally, luteolin inhibited proliferation, invasion, and metastasis in A375 melanoma cells by downregulating MMP2 and MMP9 and upregulating TIMP-1 and TIMP-2 expression levels." (PMID 40066127, 2024). "Induced overexpression of TIMP-2 suppressed melanoma cell growth but not metastatic activity, which was attributed to the TIMP-2 mediated ability of TIMP-2 to occluding interstitial collagen." (PMID 39594665, 2024). "TIMP-2, which was first identified from melanoma cells, is expressed in most tissues without being induced by growth factors." (PMID 39769318, 2024). "Compared to melanomas demonstrating segmental regression and melanomas without regression, melanomas with partial regression have nonregressing components that are overexpressed with TIMP2." (PMID 36975387, 2023). "Similarly, Alteronol was shown to inhibit cell invasion/migration in vitro and lung metastasis in vivo in murine melanoma B16F10 and B16F1 cells through a mechanism related to MMP2 reduction plus tissue inhibitor of metalloproteinases-2 (TIMP-2) induction." (PMID 33224877, 2020). "In addition, treatment with N-glycans derived from theses glycosaminoglycan increased activities of TIMP-2 in HMVEC cells pretreated with TNF-alpha and in melanoma cells, suggesting that they had anti-inflammatory and anticancer activities." (PMID 30611221, 2019). "All these reasons should be taken into account, when considering why we did not obtain high level of TIMP2 protein expression in B16-F10 melanoma tumors." (PMID 27088717, 2016). "Furthermore, in transgenic MT/RET mice characterized by the development of MT-overexpressing malignant melanomas, an increase in MMP2 and a decrease in TIMP2 expression has been noted." (PMID 25933064, 2015).
melanoma (continued). "Additionally, the canonical RECK expression levels positively correlated with TIMP-3 expression, as we have previously reported in a melanoma progression model, and RECK, RECK-B and RECK-I expressions levels correlated positively with TIMP-2." (PMID 26431549, 2015). "As an important adjustor, PI3-K directly affects the cooperative interactions of MT1-MMP and MMP-2 activity in highly aggressive melanoma cells, and regulates MT1-MMP activity which promotes the conversion of pro-MMP into its active conformation through an interaction with TIMP-2." (PMID 24628713, 2014). "Using stable melanoma cell lines, parental A2058, A2058T2-1 overexpressing TIMP-2, and A2058T2R-7 underexpressing TIMP-2, we demonstrate that the IL-8 secretion and IL-8 mRNA expression significantly increased in the A2058T2-1 overexpressing TIMP-2." (PMID 21152266, 2010). "A recent study has shown stimulation of melanoma cell lines by TIMPs, and that during melanoma progression growth responses to TIMP1 and TIMP2 may gradually change." (PMID 15083203, 2004). "All melanoma cell lines were positive for MTI-MMP and TIMP-2 mRNAs." (PMID 10360651, 1999). "ONCOS-207 (which expressed tissue inhibitor of metalloprotease type 2 [TIMP2]), ONCOS-209 (which expressed peptidyl arginine deiminase [PADI1]), and ONCOS-210 and ONCOS-212 (which expressed both TIMP2 and PADI1) exhibited oncolytic activity against four melanoma cell lines in vitro." (PMID 36816748, 2023). "Finally, TIMP-2 was shown to contribute to the activation of MMP-2 at the cell membrane in vitro and in vivo, and may thereby promote melanoma cell invasiveness." (PMID 33846376, 2021). "To investigate whether TIMP-2 activation of AKT is a unique feature of MCF-7 cells or results from the high levels of MT1-MMP expressed by the transfected cells, we characterized the effect of TIMP-2 on AKT activation in human MDA-MB-435 melanoma cells, which constitutively express MT1-MMP." (PMID 26331622, 2015).
liver fibrosis (50 papers, 2013 to 2026). "In all cirrhotic animals treated with IGF-I expressing vectors regression of hepatic fibrosis was associated with dampening of fibrogenic mediators, enhanced expression of MMPs and downregulation of TIMP-2." (PMID 27658043, 2016). "TIMP-2 is known not only for its role as an inhibitor of matrix metalloproteinases but also as a key player in liver fibrosis and tumor-stroma interactions." (PMID 41596621, 2026). "shHsd17b13 decreased elevated serum alanine aminotransferase (ALT), serum fibroblast growth factor 21 (FGF21) levels, and markers of liver fibrosis, for example, expression of Timp2." (PMID 40016916, 2025). "This study was conducted to quantify serum TIMP-2 levels in patients with MAFLD and to evaluate their association with key markers of liver fibrosis, including ALT, GGT, and FibroScan results." (PMID 41357032, 2025). "It caused a reduction in collagen levels, MMP-2, TIMP-2, and HSC activation and inhibited hepatic fibrosis in the CCl4 liver fibrosis rat model." (PMID 36985782, 2023). "Overexpression of miR-483 inhibits mouse liver fibrosis by targeting tissue inhibitor of metalloproteinase 2 (TIMP2) and platelet-derived growth factor-β (PDGF-β)." (PMID 37489457, 2023). "The serum level of TIMPs was suggested as an indicator of hepatic fibrosis: increased serum levels of TIMP-1 in chronic hepatitis C patients correlated with the stage of liver fibrosis, better than those of TIMP-2." (PMID 34065048, 2021). "Recently, an increase of pro-MMP-2 accompanied by increased TIMP-1 and TIMP-2 levels in NAFLD liver fibrosis has been reported." (PMID 30769840, 2019). "TIMPs are associated with the regulation of MMP activities, and particularly, TIMP-1 and TIMP-2 are reported to be highly expressed in human liver fibrosis." (PMID 31861943, 2019). "The ratio of matrix metalloproteinase-2 (MMP2) and its inhibitor TIMP2 has been found to be imbalanced in hepatic fibrosis whereas MMP-9/TIMP-1 ratio is dysregulated in liver metastasis." (PMID 30087389, 2018). "It should be noted that on histological examination and by serum liver function index measurement, AOs targeting TIMP2 not only reduced hepatic fibrosis but also acted to improve liver function." (PMID 29941814, 2018). "It has been known that the expression levels of MMP2, MMP9, TIMP1 and TIMP2 mRNAs are increased in the patients with hepatic fibrosis." (PMID 26863419, 2016). "TIMP-1 and TIMP-2 are capable of inhibiting the activities of all known MMPs and, in consistent with our results, their expressions are increased in CCl4-induced liver fibrosis." (PMID 27776513, 2016). "The expression levels of both TIMP-1 and TIMP-2 were found to be elevated in human and animal models of liver fibrosis." (PMID 27821159, 2016). "Consistent with a previous study in mice fed the MCD diet, expression levels of MMP-2, MMP-13, TIMP-1, and TIMP-2 were increased in mice with MCD diet-induced hepatic fibrosis in this study." (PMID 24066058, 2013). "That study also reported that TIMP-1 and TIMP-2 are crucial factors for promoting the progression of liver fibrosis." (PMID 24223741, 2013). "Notably, the positive correlation between TIMP-2 and FibroScan values also suggests a potential link to liver fibrosis." (PMID 41357032, 2025). "Even though angiogenesis was activated, Timp‐2, which has been previously shown to inhibit Vegf‐induced angiogenic response was upregulated and potentially protects from advanced liver fibrosis over time." (PMID 39269881, 2024). "This is in accordance with a recent study that demonstrated that silencing of PNPLA3 could effectively attenuate hepatic steatosis as well as reduce liver fibrosis via lowering Timp2 expression levels." (PMID 36403577, 2023). "Plasma levels of TIMP-2 are related to the stage of liver fibrosis." (PMID 36551935, 2022).
liver fibrosis (continued). "In addition, the staining of other HSCs activation related proteins TGF-β1, MMP-2, and TIMP-2 were more pronounced in the livers of CCl4-induced liver fibrosis mice than that in the control." (PMID 34603071, 2021). "Furthermore, the IGFBPrP1 knockdown attenuated liver fibrosis by re-establishing the MMP2/TIMP2 and MMP9/TIMP1 balance concomitant with the inhibition of HSCs activation and degradation of the ECM." (PMID 30769840, 2019). "Additionally, associations with lipid levels, white blood cell count, and neutrophils imply a link to systemic inflammation and liver fibrosis, highlighting the promising role of TIMP-2 as a noninvasive, blood-based biomarker for early detection and monitoring of liver fibrosis." (PMID 41357032, 2025). "The qPCR results showed that overexpression of miR-552-3p significantly reduced the mRNA levels of fibrotic genes (Col1a1, Col3a1, Timp-2) and inflammatory genes (Il-6, Ccl2, F4/80) in mice livers, which demonstrated that miR-552-3p could reduce liver fibrosis and inflammation in mice again." (PMID 37496991, 2023). "Similarly, the gene coding for the ECM modifying enzyme MMP2 and tissue inhibitor of MMPs-2 (Mmp2, Timp2), which respectively exert anti- and pro-fibrogenic roles in liver fibrosis, were strongly upregulated by CCL4 treatment in both Nlrc5-/- and control mice livers." (PMID 34712238, 2021). "A follow-up study demonstrated that miR-483 overexpression in CCl4-injured mouse livers inhibited liver fibrosis, with both miR-483-5p and miR-483-3p having anti-fibrotic activities that, respectively, targeted PDGF-β and TIMP2." (PMID 40002688, 2025). "The antifibrotic properties of CA were further supported by identifying many liver fibrosis-specific seed genes in PPI analysis, including TIMP2, COL6A1, and COL6A2." (PMID 37175790, 2023). "An earlier study demonstrated that miR-483 targets metalloproteinase 2 (TIMP2) and platelet-derived growth factor-β (PDGF-β), thus suppressing CCl4-mediated mouse liver fibrosis in vivo." (PMID 36980601, 2023). "We therefore examined liver fibrosis markers in both the CBDL and CCl4 models of liver injury and in both cases found a more severe damage and fibrosis with increased TIMP-2, Collagen-1, and ACTA-2 gene expressions." (PMID 33391458, 2021). "Similar results were shown in our CCl4 induced liver fibrosis model, as ACTA-2, TIMP-2 and Collagen-1 mRNA expression and Sirius red and α-SMA staining were similar between TLR4 KO and WT mice." (PMID 33391458, 2021). "Treatment with betulin and betulinic acid inhibited expression of TNF-α, TGF-β1, tissue inhibitor of metalloproteinase (TIMP)-1, TIMP-2, and activated matrix metalloproteinase (MMP)-2 in alcohol-induced liver fibrosis in vivo." (PMID 25897319, 2015). "Activated hepatic stellate cells contribute to liver fibrosis via abnormal production of MMP2, TIMP1, and TIMP2 through the secretion of various inflammatory cytokines from Kupffer cells and T cells." (PMID 26358689, 2015). "In this study, we demonstrated that administration of HF inhibited the expression of TIMP2, thus reduced ECM deposition within the liver parenchyma and alleviated liver fibrosis." (PMID 24358159, 2013). "In a CCL4-induced liver fibrosis model, TIMP-2 siRNA knockdown mice exhibited suppression of hepatic stellate cells and reduced collagen deposition, suggesting a pro-fibrotic role for TIMP-2." (PMID 37123405, 2023). "Also, an earlier report demonstrated that miR-483 targets TIMP2 and PDGF-β leads to suppressed CCl4-mediated liver fibrosis in mice, and miR-483 also targets TGFβ which is involved in fibrogenic responses in pulmonary arterial hypertension (PAH)." (PMID 36980601, 2023). "Hepatocyte-derived sEVs also promoted hepatic fibrosis in NAFLD by directly modulating HSC phenotype and up-regulating the expression of profibrogenic genes, including Col1α1, α-smooth muscle actin (αSMA), and tissue inhibitor of metalloproteinase-2 (TIMP-2)." (PMID 37180779, 2023).
liver fibrosis (continued). "We measured MMP-2, MMP-9, and their inhibitors (TIMP-1, TIMP-2) in the CCl4-induced liver fibrosis group with/without UCB-Exo treatment." (PMID 34772443, 2021). "TIMP2 has not been widely studied, though in a chemical model of liver fibrosis TIMP2 was shown to be pro-fibrotic." (PMID 33119677, 2020). "Additionally, in rat models of hepatic fibrosis, AOs have been successfully used to suppress expression of both TIMP1 and TIMP2." (PMID 29941814, 2018). "Furthermore, liver fibrosis was suppressed in the samples of F4MKO mice assessed by Sirius Red staining, along with the downregulation of key genes of fibrosis (Acat2, Col1a1, Col1a2, Timp2, and Tgfβ)." (PMID 37770480, 2023). "With the improvement in liver fibrosis, the mRNA levels of tissue inhibitor of metalloproteinase-1 (TIMP-1) and matrix metalloproteinase-2 (MMP-2), two genes involved in hepatic fibrogenesis, were found to be significantly suppressed, while TIMP-2 and MMP-13 were unaffected." (PMID 24066058, 2013).
ovarian carcinoma (40 papers, 1999 to 2026). A malignant neoplasm originating from the surface ovarian epithelium. "Knockdown of EZH2 in an epithelial ovarian cancer cell line caused an increase in TIMP2 levels along with decreased levels of the active form of the matrix metalloproteases, MMP2 and MMP9." (PMID 36359771, 2022). "Our recent study has shown that loss of TIMP-2 expression by siRNA affects ovarian cancer cell functions and chemosensitivity." (PMID 36585738, 2022). "In this study by using two powerful loss of gene expression/function techniques, siRNA and CRISPR/Cas9, we compared changes in cell function by the loss of TIMP-2 expression in the OVCAR5 ovarian cancer cell line." (PMID 36585738, 2022). "We have also shown diverse expression of TIMP-1, TIMP-2 and associated MMPs in ascites and ovarian cancer cell lines, and changes in the expression of these proteins in response to chemotherapy treatments." (PMID 36585738, 2022). "After confirming that TIMP2 is repressed by EZH2 in ovarian cancer, we subsequently investigated the underlying mechanism." (PMID 28620234, 2017). "However, limited alteration in TIMP gene amplifications, deep deletion or missense mutations changed platinum responses in ovarian cancer patients, with the majority becoming chemosensitive with alterations in TIMP-2, or -3 gene mutations." (PMID 35047406, 2021). "We also report for the first time that the suppression of TIMP-2 in ovarian cancer cell lines is associated with a loss of E-Cad mRNA expression with a corresponding increase in the mRNA expression of N-Cad, VIM and a decrease in the mRNA expression of COL12A1." (PMID 33023532, 2020). "Xiang-Yang Zeng, Xiao-Yan Jiang, Jia-Hui Yong, Hui Xie, Jing Yuan, Da Zeng, Ying-Yu Dou, Song-Shu Xiao "lncRNA ABHD11-AS1, regulated by the EGFR pathway, contributes to the ovarian cancer tumorigenesis by epigenetically suppressing TIMP2" Cancer Med." (PMID 38470371, 2024). "Treating SKOV-3 cells with either GnRH1 or GnRH2 led to reduced MMP-2 expression and increased secretion of tissue inhibitor of MMP-2 (TIMP2), both important mediators of ovarian carcinoma metastasis." (PMID 38260130, 2023). "This study investigated the role of TIMP-2 in an ovarian cancer cell line in which the expression of TIMP-2 was reduced by either siRNA or CRISPR/Cas9." (PMID 36585738, 2022). "Based on these findings it can be postulated that an array of different pathways controlling tumorigenesis can be activated according to the level of expression of TIMP-2 in ovarian cancer cells." (PMID 36585738, 2022). "EZH2 can methylate the promoter of TIMP2, thereby inhibiting TIMP2 expression and promoting metastasis in ovarian cancer." (PMID 35414793, 2022). "The potential use of TIMP2 as a therapeutic target in chemoresistant ovarian cancer is also considered." (PMID 36012171, 2022). "In our previous study we have shown that knockdown of TIMP-2 by siRNA resulted in the induction of an EMT-like process in ovarian cancer cell lines (OVCAR4 and JOSH2)." (PMID 36585738, 2022). "In our study, we also noted an increase in the expression of TIMP2 and 3 in fibroblasts after treatment with exosomes isolated from ovarian cancer cells." (PMID 36012171, 2022). "The role of TIMP2 in the regulation of proliferation, invasion and chemoresistance in ovarian cancer cells is also attributed." (PMID 36012171, 2022). "Based on the available knowledge and the research results obtained by us, it is possible to assume and try to extend the scope of research to search for new therapeutic drugs in cisplatin-resistant ovarian cancer, where the therapeutic target will be TIMP2." (PMID 36012171, 2022). "In conclusion, the findings described demonstrate a complex role of TIMP-2 in ovarian cancer progression." (PMID 36585738, 2022). "Previous studies have reported expression of TIMP-2 in the stroma of tumors and positively correlated that with better survival rate in ovarian cancer patients." (PMID 35047406, 2021).